CTLA4 (cytotoxic T-lymphocyte associated protein 4)
Diseases named in the same sentence as CTLA4 in open-access papers (continued):
Sharing a sentence is not in itself a finding about the gene and the disease.
autoimmune disease (continued). "In addition, the National Comprehensive Cancer Network recommends the involvement of a multidisciplinary team that includes an autoimmune disease specialist in the decision to initiate ICIs and, when possible, the avoidance of combination therapy with PD1/PD-L1 and CTLA-4 agents." (PMID 35911382, 2022). "However, to rule out a possible link between CTLA-4 and the co-occurrence of autoimmune diseases and T1DM, further genetic studies are necessary." (PMID 33272321, 2020). "The distinct functions of CTLA-4 and PD-1 are reflected in the different phenotypes seen in knockout mouse models: The mice lacking the CTLA-4 gene die from lymphoproliferation and fatal multiorgan tissue destruction, whereas the mice lacking PD-1 are variable, showing autoimmune diseases." (PMID 31487832, 2019). "On the other hand, some other subsets of Treg cells that do not express CTLA‐4 but utilise other mechanisms of suppression may be required to prevent other autoimmune diseases." (PMID 29484183, 2018). "CTLA-4 acts as an inhibitor of autoimmunity, and the defects in the B7-CD28/CTLA-4 pathway may lower the threshold of autoreactive lymphocyte activation and which in turn may lead to the development of an autoimmune disease." (PMID 29850619, 2018). "In future studies, the role of PTPN22 in the process of autoimmune tolerance breaking during the initial phase of autoimmune disease as well as the negative immunoregulatory effect of the CTLA-4 gene should be determined to reveal the common mechanisms of these diseases." (PMID 28133421, 2017). "It is also not clear whether patients with specific types of autoimmune disease are more likely to respond to anti-CTLA-4 antibody therapy." (PMID 25992290, 2015). "However, since a key role of CTLA-4 is to enable Treg suppression of autoreactive T cell activation at the costimulatory level of DC, it was no surprise that opportunistic autoimmune disorders surfaced as prominent irAEs from CTLA-4 blockade." (PMID 24904570, 2014). "Importantly, CTLA-4 polymorphisms have been linked to autoimmune conditions including type I diabetes, Hashimoto's thyroiditis, systemic lupus erythematous and celiac disease, indicating possible roles for non-hematopoietic tissue CTLA-4 in the ontogeny and progression of autoimmune disease." (PMID 33384695, 2020). "Thus, any use of CTLA-4 or OX40 Abs as adjuvants for Env vaccination will have to be used transiently and it will be important to clearly demonstrate that, as used, there is no induction of manifestations of autoimmune disease." (PMID 32075963, 2020).
Autoimmunity (400 papers, 2004 to 2026). The occurrence of an immune reaction against the organism's own cells or tissues. "BACKGROUND: Cytotoxic T-lymphocyte–associated protein 4 (CTLA-4) haploinsufficiency is a primary immune-regulatory disorder characterized by T-cell overactivation and multisystem autoimmunity." (PMID 41582224, 2026). "CTLA4 deficiency is a rare primary immune syndrome that leads to excessive T cell activation, contributing to autoimmunity and lymphoproliferation." (PMID 41571434, 2026). "The immune checkpoint receptor CTLA4, whose deficiency causes severe autoimmunity, undergoes rapid ubiquitin-dependent lysosomal degradation, making it one of the most short-lived transmembrane proteins." (PMID 41571434, 2026). "In these large deletions, the loss of CTLA4 causes haploinsufficiency resulting in a CVID-like disorder with severe autoimmunity associated with hypogammaglobulinemia." (PMID 40948799, 2025). "This abnormal CTLA-4 interferes with B- and T-cell responses causing predisposition to autoimmune conditions." (PMID 41148805, 2025). "Il-17-mediated autoimmunity and inflammation are closely linked with the administration of anti-PD-1/PD-L1 or anti-CTLA-4 antibodies in the therapeutic management of malignant neoplasms." (PMID 40376586, 2025). "In these kindreds, the heterozygous CTLA4 mutation appears to be the critical mutation resulting in severe autoimmunity." (PMID 40948799, 2025). "Self-tolerance in humans is partially maintained by the inhibition of auto-reactive T-cells through the CTLA-4 and PD-1/PD-L1 axes, and polymorphisms of PD-1 and CTLA-4 are associated with various autoimmune conditions." (PMID 40227458, 2025). "LRBA deficiency thus also results in reduced CTLA4 expression, impairing immunoregulation and predisposing patients to autoimmunity." (PMID 41515894, 2025). "The mutation truncates the cytoplasmic tail, reducing CTLA-4 stability and transendocytosis, consistent with haploinsufficiency and autoimmunity." (PMID 41608053, 2025). "Germline deletion or Treg-specific loss of CTLA-4 leads to fatal autoimmunity resembling that in scurfy mice." (PMID 41567805, 2025). "IL-17-mediated autoimmunity and inflammation is closely linked to the administration of anti-PD-1/PD-L1 or anti-CTLA-4 antibodies." (PMID 40376586, 2025). "Heterozygous CTLA4 mutations have been implicated in the emergence of a complex immune dysregulation syndrome with features of autoinflammation, autoimmunity and immunodeficiency, as well as an increased risk of cancer development." (PMID 38792965, 2024). "Programmed cell death-1 (PD-1), programmed cell death-ligand 1 (PD-L1), and cytotoxic T lymphocyte-associated antigen-4 (CTLA-4) are key in regulating immune responses to prevent autoimmunity." (PMID 39337402, 2024). "By inhibiting cytotoxic T-lymphocyte-associated protein-4 (CTLA-4) or programmed death protein-1 (PD-1), T-cells enhance the body's immune response to fighting cancer cells, protecting against autoimmunity, and simultaneously maintaining self-tolerance." (PMID 39421105, 2024). "Immune checkpoint receptors, like programmed death receptor 1 (PD‐1) and cytotoxic T‐lymphocyte associated antigen 4 (CTLA‐4) are found on T cells and play a role in the regulation of immune responses and the prevention of autoimmunity." (PMID 39560155, 2024). "These include LRBA, a member of the same BEACH domain family as NBEAL2, recessive mutations of which cause autoimmunity and lymphocytic infiltration through defective CTLA-4 trafficking." (PMID 37349339, 2023). "In humans, heterozygous mutations of CTLA-4 are associated with autoimmunity (diabetes, enteropathies, and cytopenia), lymphocyte infiltrations, and progressive B lymphopenia resulting in lung infections." (PMID 37349339, 2023). "Autosomal dominant loss-of-function (LoF) variants in cytotoxic T-lymphocyte associated protein 4 (CTLA4) cause immune dysregulation with autoimmunity, immunodeficiency and lymphoproliferation (IDAIL)." (PMID 38055819, 2023).
Autoimmunity (continued). "It is thought that this regulatory function of CTLA‐4 operates constitutively in order to prevent costimulation of self‐reactive T cells in the steady state, since loss of CTLA‐4 function triggers profound autoimmunity in mice and humans." (PMID 36727298, 2023). "The autoimmune protective effects of CTLA-4 are exemplified in patients where loss of function mutations in human CTLA-4 manifests as profound autoimmunity." (PMID 36180633, 2023). "Both pathways are involved in the regulation of autoimmunity, however deficiency in CTLA‐4 and PD‐1 lead to different disease outcomes." (PMID 36727298, 2023). "Mice deficient in CTLA-4 experience lethal lymphoproliferative disorders, and those deficient in PD-1 develop accelerated autoimmunity and lethal pathology in response to acute infection." (PMID 38077329, 2023). "Our results indicate that despite normal CTLA-4 expression in Tregs, abnormally low CTLA-4 expression in a subset of conventional T cells can nevertheless be associated with the development of autoimmunity." (PMID 37349339, 2023). "We examined the full text of 5 publications remaining to summarize the most recent knowledge about CTLA4-linked autoimmunity in the pathogenesis of endometriosis and related infertility." (PMID 36142815, 2022). "Note that patients with loss of function mutations in CTLA-4 or LRBA feature autoimmunity, hypogammaglobulinemia, respiratory infections, and enteropathies, in line with a homeostatic role of CTLA-4 in the control of immune function." (PMID 35408889, 2022). "These individuals suffer from a variety of autoimmune features and we show in the present study that patient-derived CTLA-4 Arg70Gln mutations associated with autoimmunity lose the ability to transendocytose CD86." (PMID 35999394, 2022). "Surface expression of CTLA-4 is strictly regulated in T cells, and failures in the transport mechanism of CTLA-4 to the cell surface can cause susceptibility to autoimmunity." (PMID 36613701, 2022). "In humans, inherited genetic heterozygosity for CTLA4 inactivating mutations results in immunodeficiency and autoimmunity." (PMID 35912205, 2022). "From the initial pool of 73 publications identified and screened, we finally included 5 articles to summarize the most recent knowledge about CTLA4-linked autoimmunity in the pathogenesis of endometriosis and related infertility." (PMID 36142815, 2022). "Cytotoxic lymphocyte antigen-4 (CTLA-4) is a negative regulator of T cell proliferation, thus conferring susceptibility to autoimmunity." (PMID 33748819, 2021). "Human patients with heterozygous loss of function mutations in CTLA-4 developed widespread autoimmunity including autoimmune hepatitis, T1D, and arthritis." (PMID 33692958, 2021). "Recent data confirm that carriers of the risk alleles PTPN22 1858T and CTLA4 CT60 are more prone to develop several autoimmune conditions." (PMID 33966174, 2021). "An argument for the first line of thought is that a particular loss of CTLA-4 in Treg cells was enough to induce abnormal T-cell activation and autoimmunity." (PMID 33809974, 2021). "Consideration should be given to screening for CTLA-4 variants in individuals with a history compatible with autoimmunity and CNS inflammatory disease, particularly following exclusion of lymphoma." (PMID 34097529, 2021). "This link became more apparent in studies of patients with CTLA4 haploinsufficiency, who present with a complex syndrome including autoimmunity and an increased risk for gastric cancer and lymphoma." (PMID 34235145, 2021). "Increased effector T-cell counts, lymphocytic organ infiltration, as well as multiple types of autoimmunity are commonly observed in patients with CTLA-4 insufficiency, LRBA deficiency, or DEF6 deficiency." (PMID 33996698, 2021).
Autoimmunity (continued). "Patients with mutations in the LRBA gene (encoding the lipopolysaccharide-responsive and beige-like anchor protein) have a syndrome of lymphoproliferation, humoral immune deficiency, and autoimmunity; they also show CTLA4 loss." (PMID 33435309, 2021). "CTLA-4 gene mutations in humans result in autosomal-dominant widespread autoimmunity, including AIH." (PMID 34948375, 2021). "CTLA4 HI (termed as CTLA4 deficiency) results in a hyperactivated immune system with T-cell infiltration in organs, autoimmunity, or both." (PMID 35087518, 2021). "Animal models have shown that germ-line deficiency of CTLA-4 in mice leads to extensive T cell lymphoproliferative disease, which is rapidly fatal, as well as autoimmunity." (PMID 34201529, 2021). "Given that lymphoma occurs with increased incidence in patients with autoimmunity including CTLA-4 variants, there should be a low threshold to pursue a tissue diagnosis where there is evidence of neuroinflammation." (PMID 34097529, 2021). "We found a strong association of the autoimmunity risk alleles in CTLA4 rs3087243-G and PTPN22 rs2476601-A with ITO ME/CFS." (PMID 32328064, 2020). "The expression of CTLA-4 on Tregs directly influenced its homeostasis and the function of preventing autoimmunity, the loss of CTLA-4 promoted the expansion of Tregs." (PMID 33123120, 2020). "Loss of CTLA-4 in mice and heterozygous mutations in humans reveal profound autoimmunity where enteropathy is a consistent feature." (PMID 33223527, 2020). "In conclusion, our study shows that the PTPN22 rs2476601 and CTLA4 rs3087243 autoimmunity risk variants are more frequent in patients with ITO ME/CFS." (PMID 32328064, 2020). "Analysis of 305 ME/CFS patients and 201 healthy controls showed significant associations of the PTPN22 rs2476601 and CTLA4 rs3087243 autoimmunity-risk alleles with ME/CFS." (PMID 32328064, 2020). "Here the authors identify homozygous DEF6 mutations in patients with severe autoimmunity, one of which received and responds to CTLA-4-Ig, and show that DEF6 is crucial for CTLA-4 cell surface trafficking and immune regulatory function." (PMID 31308374, 2019). "Our discovery of a mechanistic link between DEF6 mutations and CTLA-4 functional integrity offers insights to autoimmunity in humans." (PMID 31308374, 2019). "Variants in immune-modulating genes (such as FOXP3, CD25, CD40, CTLA4, and HLA) have also been recognized as risk factors for different autoimmune disorders in case–control studies." (PMID 29931474, 2018). "The immune system is complicated and thus needs checkpoints to prevent autoimmunity, such as cytotoxic T lymphocyte-associated antigen 4 (CTLA4, CD152) and programmed cell death protein 1 (PD-1)." (PMID 29403493, 2018). "Nevertheless, ALPS patients do not present with clinical features observed in “Tregopathies” (i.e., FOXP3 or CTLA-4 deficiencies) such as lymphocytic tissue infiltrations and organ-specific autoimmunity, in particular autoimmune enteropathy." (PMID 29686686, 2018). "Heterozygous mutations in the cytotoxic T lymphocyte antigen-4 (CTLA-4) are associated with lymphadenopathy, autoimmunity, immune dysregulation, and hypogammaglobulinemia in about 70% of the carriers." (PMID 29375547, 2017). "The combination of both mutations correlates with immunodeficiency associated with lymphadenopathy, autoimmunity, and hypogammaglobulinemia, whereas carriers of either the CTLA-4 or the JAK3 single mutations are healthy." (PMID 29375547, 2017). "Checkpoint molecules, particularly cytotoxic T-lymphocyte-associated protein 4 (CTLA-4) and programmed death-1 (PD-1), play a key role in downregulating T cell activation, maintaining self-tolerance and limiting autoimmunity." (PMID 30886946, 2017). "Immune checkpoints or coinhibitory receptors have a central role in regulating autoimmunity, and deficiency of CTLA-4 develops profound lymphoproliferation and systemic autoimmune disease." (PMID 28545567, 2017).
Autoimmunity (continued). "In both CTLA4-deficient and Foxp3-deficient mice, autoimmunity is driven by CD4 effector pathology, and depletion of Tregs in adult mice is associated with rapid onset of autoimmune pathology." (PMID 28646041, 2017). "CTLA-4 is a coinhibitory protein required for regulation of T-cell activation and CTLA-4 deficiency in mice is associated with fatal lymphoproliferation, intestinal inflammation and autoimmunity." (PMID 28561062, 2017). "The autoimmunity-susceptible SNPs in this region (rs231775, rs3087243, and rs231806) have been associated with various functional effects including CTLA4 transcript levels, splicing, production of the soluble form of CTLA-4 and posttranslational modifications." (PMID 28248954, 2017). "Several of studies have notified the correlation between CTLA-4 lymphocyte variants and its susceptibility to autoimmunity and cancer." (PMID 28211499, 2017). "Although the autoimmunity seen in mice is less severe with adult CTLA4 depletion, haploinsufficiency of CTLA4 has been associated with human autoimmunity, so it is likely in humans that CTLA4 blockade also drives significant autoimmunity." (PMID 28646041, 2017). "In relation to that, several studies have shown that certain polymorphisms in the CTLA-4 gene are significantly associated with susceptibility to autoimmunity." (PMID 28589115, 2017). "CTLA-4 gene polymorphisms have been associated with numerous autoimmune conditions, including diabetes and inflammatory bowel disease." (PMID 26863566, 2016). "One study focusing on this polymorphism and CTLA4 protein expression showed that the -318T allele is associated with higher promoter activity and thus reduced autoimmunity." (PMID 27111218, 2016). "Two unrelated patients with low B cells and severe autoimmunity had novel mutations in the regulatory receptor CTLA4 gene." (PMID 27379089, 2016). "These Ts maintained high expression levels of latency-associated peptide (LAP), CD103, PD-L1, and CTLA-4 following transplantation and completely inhibited autoimmunity." (PMID 27965674, 2016). "In summary, multiple studies have implicated both the CTLA-4 and PD-1 pathways in the pathogenesis of T1D and suggest a synergistic relationship between these two negative regulatory receptors to potentiate autoimmune disorders." (PMID 28031819, 2016). "Overall, our study has provided new insights into the regulation of CTLA-4, a critical suppressive protein whose loss of function is associated with autoimmunity." (PMID 26134669, 2015). "Recently, we and others observed CTLA-4 genetic variants that affected the level of CTLA-4 protein in autoimmunity and immunodeficiency, which indicates the importance of CTLA-4 expression in controlling human disease." (PMID 26134669, 2015). "This notion is supported by the phenotype shown by CTLA-4 deficient mice, which develop massive lymphoproliferation and autoimmunity." (PMID 25229821, 2014). "Site number in CTLA-4 is critical to T cell arrest, and a deficiency in sites contributes to autoimmunity." (PMID 24475074, 2014). "Because of its inhibitory role, CTLA-4 is a strong candidate susceptibility gene in autoimmunity and several studies suggest disease associated polymorphisms." (PMID 24605322, 2014). "As with CTLA-4, PD-1-deficient mice also develop autoimmunity, but the disease is less severe and occurs later in life." (PMID 24353898, 2013). "Equally critical for immune regulation is the T cell inhibitory protein CTLA-4, deficiency of which triggers lethal autoimmunity." (PMID 23849743, 2013). "CTLA-4-deficient mice develop a rapidly lethal T cell-mediated autoimmunity, which clearly demonstrates the importance of CTLA-4 in down-regulating T cell activation." (PMID 24353898, 2013). "The CTLA-4 protein can transmit an inhibitory signal to T-cells and has a strong susceptibility in autoimmunity." (PMID 23181132, 2012). "Since the CTLA-4 protein transmits an inhibitory signal to T-cells, it has a strong susceptibility in autoimmunity." (PMID 23181132, 2012).